RNU6-1086P (RNA, U6 small nuclear 1086, pseudogene)
Gene: Small nuclear RNA gene on chromosome 8 (27,679,836 to 27,679,935, forward strand). Ensembl gene ENSG00000222862.
Homologues: Orthologues: chimpanzee U6 (97% identical), macaque U6 (90% identical), pig U6 (77% identical). Paralogues in human: RNU6-1011P (82% identical), RNU6-38P (82% identical), RNU6-950P (82% identical), RNU6-1075P (81% identical), RNU6-1124P (81% identical), RNU6-1145P (81% identical), RNU6-1158P (81% identical), RNU6-29P (81% identical), RNU6-338P (81% identical), RNU6-39P (81% identical), RNU6-41P (81% identical), RNU6-49P (81% identical), and 1283 more.